SOX9 (SRY-box transcription factor 9)
Diseases named in the same sentence as SOX9 in open-access papers (continued):
Sharing a sentence is not in itself a finding about the gene and the disease.
lung carcinoma (continued). "To further confirm the role of SOX9 in TGF-β-mediated induction of EMT-like phenotype in lung cancer cells, we inhibited SOX9 expression using RNAi in A549 and H1299 cells, which were then co-cultured with macrophages." (PMID 29245941, 2017). "In recent years, research has focused on the role of SOX9 in tumors, and abnormal SOX9 expression occurs in many cancer types, especially in lung cancer." (PMID 29245941, 2017). "In this study, MALAT1, miR-101 and SOX9 formed a feedback loop, which plays a crucial role in regulating the chemo-resistance of lung cancer cell through activation of chemo-resistance-related Wnt signaling pathway." (PMID 29212230, 2017). "In this study, we found that lung cancer cells promoted the M2 polarization of tumor-associated macrophages (TAMs), which in turn secretes TGF-β and promotes SOX9 expression via the C-jun/SMAD3 pathway, thereby promoting tumor metastasis." (PMID 29245941, 2017). "We also examined clinical specimens and found that TGF-β and SOX9 were highly expressed in cancerous tissues from patients with advanced lung cancer." (PMID 29245941, 2017). "We also used an established NSCLC cell line H460 to compare the results of SOX9 downregulation in BSW cells to those in lung cancer cells." (PMID 28912540, 2017). "Our data proved that RMRP acted as an oncogene LncRNA to promote the expression of KRAS, FMNL2 and SOX9 by inhibiting miR-206 expression in lung cancer." (PMID 27906963, 2016). "Capaccione and colleagues demonstrated that SOX9 is overexpressed in lung adenocarcinoma and induces lung cancer cell motility and invasion." (PMID 26384302, 2015). "To further investigate Sox9 overexpression in lung ADC, we queried data with annotated mutational information and analyzed Sox9 expression within lung cancer genetic subgroups, including EGFR and KRAS mutations." (PMID 25004243, 2014). "In lung cancer, Sox9 overexpression was recently shown to increase cell proliferation and xenograft tumor formation." (PMID 25004243, 2014). "We observed that Sox9 is a potent inducer of lung cancer cell motility and invasion, and a negative regulator of E-cadherin, a key protein that is lost during epithelial-mesenchymal transition (EMT)." (PMID 25004243, 2014). "Correlating to the transforming capacity, absence of p38 activity induces an upregulation of the expression of the stem and lung cancer marker Sox9 in K-RasG12 cells supporting its potential as a therapeutic target." (PMID 24265727, 2013). "Immunohistochemical analysis demonstrated a high expression of SOX9 in 74/142 (52.1%) paraffin-embedded archival lung cancer biopsies." (PMID 22385677, 2012). "In a more detailed survival study, univariate and multivariate analyses demonstrated that high expression of SOX9 is a predictor of poor prognosis for lung-cancer patients." (PMID 22385677, 2012). "Comparative analyses of SOX9 mRNA and protein in lung cancer tissues and their paired adjacent normal tissue have provided strong support for the identified upregulation of SOX9 in NSCLC." (PMID 22385677, 2012). "Knockdown of SOX9 has been found to decrease the proliferation rate of lung cancer cell lines and significantly attenuate the tumorigenicity of lung adenocarcinoma." (PMID 22385677, 2012). "Log-rank test and Kaplan-Meier analysis were also applied to evaluate further the effect of SOX9 expression and histological staging of lung cancer on survival." (PMID 22385677, 2012). "SOX9 in lung cancer cell lines was upregulated at both mRNA and protein levels, and SOX9 mRNA and protein were also elevated in NSCLC tissues compared with levels in corresponding adjacent non-cancerous lung tissues." (PMID 22385677, 2012). "Abnormal SOX9 expression occurs in different types of cancers, and thereby, the TGFβ/SOX9 axis may be an effective therapeutic target for lung cancer." (PMID 39083441, 2025).
lung carcinoma (continued). "Furthermore, SOX9 has been linked to radiotherapy resistance in HNSCC and to resistance to cisplatin therapy in non‐small cell lung cancer." (PMID 39180200, 2025). "Tumor suppressor miR-133b in lung cancer was associated with the WNT pathway and SOX9." (PMID 38473318, 2024). "In a study of lung cancer, miR-133b is shown that up-regulation of miR-133b reduces cell proliferation, induces cell apoptosis and G0/G1 phase arrest, and decreases cell invasion by inhibiting SOX9/b-catenin signaling." (PMID 38231064, 2024). "Additionally, M2 macrophages can also secrete TGF-β to induce Sox9 expression in lung cancer cells through the c-Jun/Smad3 pathway, thereby inducing EMT and enhancing lung cancer cell migration." (PMID 38840908, 2024). "Previous literature has reported an interdependent protein interaction between SLUG and SOX9 in mammary stem cells, human lung carcinoma and kidney fibrosis, whereby inhibition of either SLUG or SOX9 resulted in inhibition of the mammary bipotent stem cells or cancer cells." (PMID 33963183, 2021). "Similarly, SLUG is required for SOX9 stabilization, which promotes CSCs and metastasis in lung cancer." (PMID 34809669, 2021). "SOX9 is well studied in cancer chemotherapy, and its high expression and activation have been proven to promote cell resistance to chemotherapy in multiple types of cancers, including lung cancer." (PMID 34899911, 2021). "In accordance with these findings, the depletion of endogenous KEAP1 by short hairpin RNA (shRNA)‐mediated knockdown or CRISPR‐mediated knockout in multiple liver and lung cancer cell lines led to a marked increase in the abundance of SOX9 protein, but not its mRNA levels." (PMID 33173725, 2020). "Since SOX9 is known as a TF and former report has determined that SOX9 is responsible for the upregulation of lncRNA MALAT1 in lung cancer, we asked whether SOX9 could transcriptionally regulate SOX9‐AS1 expression in HCC." (PMID 31402556, 2019). "miR-592 functioned as a tumor suppressor in lung cancer by targeting SOX9." (PMID 29743816, 2018). "SNHG1 could promote NSCLC progression of lung cancer via miR-101-3p/SOX9/Wnt/β-catenin regulatory network and miR-145-5p/ MTDH axis." (PMID 29872497, 2018). "Because number of TAMs and SOX9 expression were closely related in lung cancer patients, we hypothesized that TAMs may directly affect SOX9 expression in lung cancer cells." (PMID 29245941, 2017). "Expression of the SOX9 transcription factor has also recently been observed in lung cancer." (PMID 29245941, 2017). "The SNHG1/miR-101-3p/SOX9/Wnt/β-catenin axis regulatory network might provide a potential new therapeutic strategy for lung cancer treatment." (PMID 28147312, 2017). "SOX9 is widely expressed in lung cancer cells and promotes tumor proliferation and metastasis." (PMID 29245941, 2017). "We also investigated the relationship between macrophages and SOX9 expression in lung cancer cells." (PMID 29245941, 2017). "Taken together, these results indicate that TAMs promote tumor metastasis via a TGF-β/SOX9 axis in lung carcinoma; this axis might therefore be a target for lung cancer treatments." (PMID 29245941, 2017). "Together, the results identify a new functional role for a Notch1-Sox9 signaling axis in lung ADC that may explain the correlation of Sox9 with tumor progression, higher tumor grade, and poor lung cancer survival." (PMID 25004243, 2014). "Conversely, in the murine model of Notch1-induced lung cancer, Sox9 is overexpressed as early as 7 days after induction of Notch1 overexpression in the alveolar epithelium, specifically confined to the alveolar hyperplastic regions, and thus is likely to be directly downstream of Notch." (PMID 25004243, 2014). "Similar results were observed in A549 and H1650 cells, but not in H358 cells, suggesting that other upstream pathways might also drive Sox9 expression in lung cancer." (PMID 25004243, 2014).
lung carcinoma (continued). "Sox9 expression correlates with Notch signaling in humans, but there has been a lack of direct evidence that Notch-induced modulation of Sox9 expression is evolutionarily conserved in humans or that Sox9 is a Notch target in lung cancer." (PMID 25004243, 2014). "Other than the Sox2 and Sox4, Sox9 and Sox18 also showed oncogenetic properties in lung cancer." (PMID 23443092, 2012). "SOX9 protein and mRNA expression in normal human pneumonocytes, lung cancer cell lines, and eight pairs of matched lung cancer tissues and their adjacent normal lung tissues were detected by Western blotting and real-time reverse transcription-polymerase chain reaction (RT-PCR)." (PMID 22385677, 2012). "Moreover, Sox9 is closely related to lung regeneration and lung cancer in patients." (PMID 34215344, 2021). "The TGF-β/SOX9 axis may therefore be an effective target for the treatment of lung cancer." (PMID 29245941, 2017). "Taken together, MALAT1, miR-101 and SOX9 form a feedback loop to enhance the chemo-resistance of lung cancer cell to DDP; this MALAT1-miR-101-SOX9 feedback loop plays an important role in the chemo-resistance of lung cancer cell to DDP and may serve as a potential target for cancer treatment." (PMID 29212230, 2017). "We hypothesized that TGF-β induces EMT in lung cancer cells by increasing SOX9 expression." (PMID 29245941, 2017). "It should be noted that the level of SOX9 protein in the NSCLC cell lines and clinical lung cancer tissues was paralleled with the mRNA expression level, indicating the possibility that the increase of SOX9 in NSCLC might be largely attributable to regulation at the mRNA level." (PMID 22385677, 2012). "In lung cancer, SOX2 interacts with HDAC1 to inhibit SOX9 expression, while inhibition of HDAC1 increases SOX9 expression." (PMID 39372390, 2024). "When SNAI2 and SOX9 are co-expressed in human lung carcinoma, SNAI2 can protect SOX9 avoid from ubiquitin-mediated proteasomal degradation, which is necessary for SOX9 to promote cancer stem cells and maintain its stem-like phenotype." (PMID 36674577, 2023). "ADCK5 phosphorylates Sox9 and thereby regulates PTTG1 in lung cancer cells, which leads to a change in the migrative and invasive behavior of these cells." (PMID 35205819, 2022). "TGF-β secreted by TAMs upregulates SOX9 expression, which promotes EMT and enhances tumor cell proliferation, migration, and invasion in lung cancer via the TGF-β/SOX9 axis." (PMID 34439281, 2021). "These processes contributes to the growth of lung cancer spheres via SOX9-mediated stem-like properties, suggesting that HDAC10-TGF-β-SOX9-SLUG/CD44 axis plays an essential role in lung adenocarcinoma." (PMID 33997894, 2021). "Next, we explored the physiological roles of degron‐mediated SOX9 degradation by KEAP1 in HCC and lung carcinoma." (PMID 33173725, 2020). "Given the critical oncogenic role of SOX9 and the high frequency of KEAP1 mutations in lung carcinoma and HCC, our study suggests an optimal treatment strategy based on genetic status, which may provide stratified clinical treatments for individual lung carcinoma or HCC patients." (PMID 33173725, 2020). "Altogether, these data suggest that CUL3KEAP1 suppresses cancer progression largely through promoting Sox9 poly‐ubiquitination and degradation in the HCC and lung carcinoma setting." (PMID 33173725, 2020). "TGF-β produced by TAMs increased SRY-Box Transcription Factor 9 (SOX9) expression via the C-jun/SMAD3 pathway, which promoted cancer cell invasion in lung cancer metastasis." (PMID 32326073, 2020). "Therefore, TGF-β/SOX9 axis may represent an effective therapeutic target for lung cancer." (PMID 33224886, 2020). "TAMs secreted TGF-β, which increased SOX9 expression and promoted epithelial-to-mesenchymal transition (EMT) in lung cancer cells, thereby promoting tumor proliferation, migration, and invasion." (PMID 29245941, 2017).
lung carcinoma (continued). "A number of established lung cancer oncogenes have also been included in the classifier, such as IL1R2, JUNB, EGFR, SOX9, FOSB, and JUND." (PMID 27935865, 2017). "Macrophages promoted SOX9 expression and transformation into an EMT-like phenotype in lung cancer cells." (PMID 29245941, 2017). "miR-206 was proved to act as a tumor suppressor miRNA in lung cancer through targeting the KRAS, FMNL2 and SOX9." (PMID 27906963, 2016). "The data show that upregulation of SOX9 mRNA and protein is a common and frequent event in both NSCLC cell lines and human lung cancer tissues." (PMID 22385677, 2012). "SOX9 has previously been shown to be highly expressed in aggressive cancers and has also been identified as a negative prognostic factor for lung cancer." (PMID 35700516, 2022). "We found that silencing NRF2 through shRNA had no obvious effect on SOX9 mRNA levels in human lung cancer cell line‐H1299, as determined by qRT‐PCR." (PMID 33173725, 2020). "Subsequently, we validated this finding further in the H1299 lung cancer cells by showing the same set of five KEAP1 mutants failed to destabilize endogenous SOX9." (PMID 33173725, 2020). "In addition, we found that TGF-β secreted by TAMs increased SOX9 expression and promoted EMT in lung cancer cells by activating the C-Jun pathway." (PMID 29245941, 2017). "Therapies that target the TGF-β-SOX9 axis to inhibit EMT, which promotes proliferation and metastasis, in lung cancer cells might therefore be effective treatments for NSCLC." (PMID 29245941, 2017). "In addition to the interaction with miR-101, SOX9 binds to the promoter of MALAT1 to promote MALAT1 expression, thereby enhancing the chemo-resistance of lung cancer." (PMID 29212230, 2017). "Lung cancer cells also promote M2 polarization of TAMs, and the secretion of TGF-β by TAMs activates the c-Jun and Smad3 pathways in lung cancer cells, leading to increased expression of SOX9, thereby facilitating epithelial-mesenchymal transition (EMT), tumor proliferation, migration, and invasion." (PMID 40787464, 2025). "Furthermore, the lung carcinoma datasets from cBioPortal showed that SOX9 mRNA levels did not correlate with PRMT7 mRNA levels." (PMID 41428171, 2025). "Furthermore, the lung carcinoma datasets from The Cancer Genome Atlas (TCGA) showed that NRF2 or KEAP1 mRNA levels do not correlate with SOX9 mRNA levels." (PMID 33173725, 2020). "In addition, by analyzing the TCGA human lung cancer dataset, we found that the advanced‐stage tumors (clinical stage IV disease) were significantly enriched for the human KEAP1‐mutant transcriptional signature, and core SOX9 target genes were significantly upregulated in tumors from advanced stage." (PMID 33173725, 2020). "However, the functional role of Sox9 in lung cancer has not been fully elucidated." (PMID 25004243, 2014). "This revealed that SOX9 levels were higher in advanced stages of the disease, supporting the hypotheses that SOX9 may play a role in the progression of NSCLC and that it could represent a biomarker that identifies subsets of lung-cancer patients with more aggressive disease." (PMID 22385677, 2012).
prostate carcinoma (70 papers, 2008 to 2026). A carcinoma that arises from epithelial cells of the prostate gland. "SOX9 is known for stemness maintenance, prevention of stem-like cell differentiation in various tumors, and is associated with prostate cancer progression and treatment resistance." (PMID 41041045, 2025). "The SOX2 and SOX9 genes are overexpressed in advanced prostate cancer and SOX9 is linked to decreased response to early treatment and to biochemical recurrence." (PMID 35682963, 2022). "Loss of LRF in prostate cancer cells activates SOX9, a key driver of aggressive prostate cancer by promoting invasion, cell fate and cytoskeleton alterations and epithelial to mesenchymal transition." (PMID 31366128, 2019). "SOX9 has been implicated in prostate cancer, with high levels of SOX9 found in early stages of prostate neoplasia and high grade PIN in mice and associated with increasing Gleason grade in humans." (PMID 29484136, 2018). "In xenograft models of prostate cancer, increased expression of SOX9 causes cancer growth, invasion and angiogenesis, while silencing of SOX9 dramatically decreases tumor growth." (PMID 27863438, 2016). "In summary, the results of our study argue against a tumor-promoting role of SOX9 in prostate cancer, but demonstrate that loss of SOX9 expression characterizes a particularly aggressive subset of ERG positive cancers harboring PTEN deletions." (PMID 26030748, 2015). "Wang and colleagues identified that loss of the zinc finger and BTB domain-containing protein 7a (Zbtb7a) gene accelerates oncogenesis in PTEN loss-driven prostate cancers via a SRY box 9 (SOX9) dependent pathway for cellular senescence bypass and invasion." (PMID 25496077, 2014). "Genetic variants in the long-range enhancer of SOX9 account for the risk associated with prostate cancer." (PMID 23690926, 2013). "Utilizing the same TAM-inducible, organ-grafting system in combination with two genetic models of prostate cancer, we found that loss of Sox9 blocked cancer formation in both the TRAMP and Hi-Myc model systems." (PMID 22761195, 2012). "To determine if Sox9 is necessary for cancer initiation in other models prostate cancer, we generated Hi-Myc prostates conditionally deficient for Sox9 expression." (PMID 22761195, 2012). "SOX9 expression has been associated with a putative subgroup of prostate cancer, associated to lymph-node metastasis (as seems to be the case in this dataset) and has a know role in chondrogenic differentiation processes." (PMID 20805891, 2010). "Furthermore, SOX9 expression was found to be linked with increasing GS as well as higher Ki67 staining in a cohort of 880 human prostate cancer samples." (PMID 31027362, 2019). "Since a previous ChIP-seq study showed that there was a weak SOX9-binding peak associated with the YAP promoter in prostate cancer cells, indicating that SOX9 may activate YAP transcription, we next assessed whether SOX9 could regulate YAP expression in ESCC." (PMID 30401982, 2019). "Moreover, Sox9 loss inhibited tumour formation in two prostate cancer mouse models (TRAMP and Myc overexpression)." (PMID 29484136, 2018). "However, recent studies examining the role of SOX9 in prostate cancer showed that overexpression was associated with a higher Gleason score, cancer progression and invasion." (PMID 27863438, 2016). "The striking limitation of the prognostic impact of SOX9 loss to the subset of ERG-positive cancers with PTEN deletions provides further evidence for the existence of clinically relevant molecularly distinct subgroups of prostate cancers." (PMID 26030748, 2015). "Due to its essential role in cancer initiation, manipulation of Sox9 targets in at-risk men may prove useful in the chemoprevention of prostate cancer." (PMID 22761195, 2012). "However, abrogation of cancer initiation in two models of prostate cancer with Sox9 loss suggests another key role for Sox9 in prostrate carcinogenesis." (PMID 22761195, 2012).